CCND1 (cyclin D1)
Diseases named in the same sentence as CCND1 in open-access papers (continued):
Sharing a sentence is not in itself a finding about the gene and the disease.
oral cancer (continued). "Additionally, CCND1 (Cyclin D1), a key cell-cycle regulator, is often overexpressed in oral cancer, driving uncontrolled cell proliferation and tumor development." (PMID 40676709, 2025). "Furthermore, astaxanthin was observed to inhibit cell divisions in a hamster model of oral cancer via the regulation of cyclin D1 action, inhibiting JAK/STAT-3 kinases and proliferating cell nuclear antigen (PCNA)." (PMID 35276890, 2022). "Inhibition of cyclin D1 is critical for destroying efficiently oral cancer cells." (PMID 34158560, 2021). "Furthermore, our study clearly demonstrates miR-31-induced downregulation of the cell-cycle regulatory molecules, including the well-established proto-oncogenes cyclin D1 (CCND1) and c-MYC, presumably linked to a delay in the cell cycle of oral cancer cells." (PMID 33007980, 2020). "The study indicated that SnO2 NP could inhibit the expression of CCND1 and c-myc in oral cancer cells, thereby exerting an inhibitory effect on cell proliferation." (PMID 32766221, 2020). "The role of CCND1 had been investigated in both HNSCCs and oral cancers." (PMID 31159251, 2019). "Expression levels of the CCND1 gene could be used as a biomarker to select oral cancer patients who could benefit from induction chemotherapy." (PMID 30417146, 2018). "Accordingly, cyclin D1 is often a target when treating oral cancer." (PMID 26449430, 2015). "The data suggest that the inactivation of GSK3, especially GSK3β, might be related to oral cancer progression and might fuel the transcription of cyclin D1." (PMID 25645517, 2015). "However, a recent study reported RNA—dependent direct physical interaction between ELAVL1 and hnRNPD in the nucleus influences the expression of cyclin D1 and p16, both of which are important for oral cancer development." (PMID 26318153, 2015). "In this study, Cyclin-D1 expression in oral cancer was observed 92%, which is higher than the 19% reported for head and neck cancer which could be the potential targets for overcoming the treatment resistance." (PMID 26675419, 2015). "However, in some other tumor types, such as oral cancer, CCND1 is part of a larger region with recurrent copy number gains on chromosome and other nearby genes have also been suggested to play a role in oncogenesis." (PMID 25078894, 2014). "In this study, no increased cancer risk was demonstrated in the smoking subgroup analysis, suggesting that smoking did not modify the effect of CCND1 polymorphisms on oral cancer risk." (PMID 23170138, 2012). "Collectively, the data failed to suggest CCND1 G870A polymorphism as a low-penetrant risk factor for developing oral carcinoma." (PMID 23170138, 2012). "In summary, despite the limitations, the results of the present meta-analysis failed to suggest a significant association between CCND1 G870A genetic variations and oral cancer risk." (PMID 23170138, 2012). "In the present study, the results of meta-analyses failed to reveal a significant association of CCND1 G870A polymorphism with oral cancer risk." (PMID 23170138, 2012). "However, reports on cyclin D1 expression and their relation to clinicopathological features and cell cycle parameters in tobacco-related oral cancer are scanty." (PMID 21537090, 2011). "Thus, in oral cancer, overexpression of cyclin D1 is more common than nuclear β-catenin expression (42% vs. 23%)." (PMID 20302655, 2010).
oral cancer (continued). "Thus strategies to prevent overexpression of cyclin D1 may be important for control of growth and metastasis of oral carcinoma." (PMID 21537090, 2011). "This may be because multiple mechanisms regulate cyclin D1 expression in oral cancer cells." (PMID 20302655, 2010). "In oral cancer and OPMD specifically, recurrent amplifications of chromosomal regions like 3p26 and 11q13 lead to overexpression of oncogenes such as CCND1, reinforcing proliferative signaling and further promoting genomic instability." (PMID 40805130, 2025). "Oral cancer overexpression 1 (ORAOV1) is located within the chromosome band 11q13, between cyclin D1 (CCND1) and fibroblast growth factor 19 (FGF19)." (PMID 41321947, 2025). "Our study revealed that Cyclin D1, CD44, MAA and SNA-1 offered a sensitivity of 89% and specificity of 92% in delineating HGD and oral cancer." (PMID 37747904, 2023). "In this study, treatment with ROS scavenger NAC reduced the levels of p-Akt, cyclin D1, PCNA, and Bcl-2 and increased the expression of Bax in oral cancer cells." (PMID 29725496, 2018). "To confirm the function of CCND1, JUN and SPP1 in oral cancer cell invasion, we knocked down expression of CCND1, JUN and SPP1 through siRNA in the human oral cancer cell line OECM-1 and examined the alteration of cell invasion ability." (PMID 30459815, 2018). "We further tried to explore the correlation of expression of CCND1, JUN and SPP1 with oral cancer metastasis through statistically analyzing the clinic data in the literature." (PMID 30459815, 2018). "In synergy with CCND1, overexpression of the PPP1CA gene, coding for the catalytic subunit of protein phosphatase 1α (PP1α), is responsible for the progression of oral cancer." (PMID 30417146, 2018). "Silencing expression of CCND1, JUN and SPP1 in the human oral cancer cell line OECM-1 confirmed that those genes play essential roles in oral cancer cell invasion." (PMID 30459815, 2018). "We focused on those 28 common DEGs that show consistent changes in both datasets and defined a “metastasis signature”: CCND1, JUN and SPP1 for oral cancer lymph node metastasis." (PMID 30459815, 2018). "CCND1 is one of the DEGS with elevated expression in both metastatic lymph nodes and metastatic primary tumor of oral cancer in our analysis." (PMID 30459815, 2018). "In a cell proliferation model, P. gingivalis promoted oral cancer cell proliferation by regulating cyclin D1 expression via the miR-21/PDCD4/AP-1 negative feedback signaling pathway." (PMID 40002861, 2025). "It even reduced the phosphorylation of ERK1/2 and AKT1 with concomitant downregulation of cyclin D1 (CCND1), cadherin 2 (CDH2), and vimentin (VIM) and upregulation of cadherin 1 (CDH1) expression suggesting its anti-proliferative and anti-EMT effects in oral cancer." (PMID 36761830, 2022). "In sum, this study identifies a unique gene signature – CCND1, JUN and SPP1 – which could be a new early biomarker for diagnosing oral cancer lymph node invasion and metastasis." (PMID 30459815, 2018). "Our study identified a novel “focal adhesion”-related gene signature (CCND1, JUN and SPP1) that might be applicable for diagnosis of oral cancer metastasis to lymph nodes." (PMID 30459815, 2018).
oral cancer (continued). "Moreover, cyclin-D1, Bcl-2, and matrix metalloproteinase-9 (MMP-9) were upregulated, and caspase-9 was downregulated, suggesting that silencing of NGAL increases oral cancer cell proliferation, survival, and migration." (PMID 29996471, 2018). "The result further supports the hypothesis that the focal adhesion-related gene signature (CCND1, JUN and SPP1) is important for oral cancer invasion." (PMID 30459815, 2018). "Our study identified a novel focal adhesion-related gene signature (CCND1, JUN and SPP1) that might be important for oral cancer metastasis to lymph nodes." (PMID 30459815, 2018). "Moreover, the expression of cyclin-D1, Bcl-2, and MMP-9 were upregulated and caspase-9 was downregulated, which are the key molecules involved in oral cancer cell proliferation, survival, invasion, and migration." (PMID 29996471, 2018). "Our study identified a unique gene signature – CCND1, JUN and SPP1 – which may be involved in oral cancer lymph node metastasis." (PMID 30459815, 2018). "Interestingly, EGFR and CCND1 oncogenic events are known to act via a common RAS-MAPK Kinase pathway to promote cell cycle and known to act as a driver of oral cancer tumorigenesis." (PMID 28939077, 2017). "This genetic signature marker contains LRP12, CCND1, EGFR and TPM2 genes that could predict clinical outcomes and facilitate selection of therapeutic strategies in oral cancer management that are tailor-made for patients." (PMID 28384287, 2017). "After initial screening of the titles and abstracts, we excluded 1633 articles either because of duplication or they did not include the topics cyclin D1 overexpression and oral cancer." (PMID 24675814, 2014). "The high expression of typical biomarkers of cell proliferation, such as cyclin D1 and PCNA, induces the propagation of unrepaired DNA damage, accumulation of genetic errors and a selective growth advantage for altered cells, thereby promoting oral cancer progression." (PMID 29725496, 2018). "We have not found similar gene expression data of CCND1 and SPP1 in oral cancer metastasis." (PMID 30459815, 2018).
neuroblastoma (72 papers, 2010 to 2025). Neuroblastoma (NB) is the most common solid, extracranial childhood tumor. "Silencing of ARID1A/B caused a strong decrease in cyclin D1 protein levels in neuroblastoma cells, with a concomitant reduction in Rb phosphorylation." (PMID 36057593, 2022). "CEND1 was shown to suppress cell proliferation via modulating the cyclin D1 pathway, which is linked to its potential tumor suppressor functions, associated with proliferation inhibition of neuroblastoma cells." (PMID 32156068, 2020). "Genetic aberrations and over-expression of the Cyclin D1 gene have been reported for several human neoplasms and neuroblastomas and elevated expression of cyclin D1 is associated with high degree of malignancy and rapid cell proliferation." (PMID 23383150, 2013). "Resveratrol caused neuroblastoma cell cytotoxicity with S-phase arrest, decreased clonal expansion, and increased mitochondria-mediated intrinsic caspase-dependent apoptosis by selectively targeting cyclin D1, Bcl-2, Bcl-xL, and Mcl-1 proteins." (PMID 38249515, 2023). "Other potential factors such as TERT rearrangements, ATRX mutations, CCND1 amplification may also perform well in prognosis of neuroblastoma." (PMID 31338261, 2019). "Mechanistically, we identify a novel PLK4-CXCR4 signaling axis that governs neuroblastoma differentiation through PI3K/Akt-mediated modulation of cyclin D1 expression." (PMID 40860200, 2025). "We have shown that Dyrk1B promotes cell cycle exit and neuronal differentiation in mouse neuroblastoma cells via cyclin D1 cytoplasmic relocation and proteasomal degradation." (PMID 38294527, 2024). "Concordantly, BAF disruption exerted a strong protein repression of cyclin D1 and downstream effectors, a regulatory axis crucial particularly for neuroblastoma cells, which have higher levels of dependency for this protein than those of other origins." (PMID 36057593, 2022). "In contrast, the results thus far have shown that GATA3 solely functions as an oncogenic factor by transactivating cyclin D1 expression in neuroblastomas." (PMID 33803938, 2021). "MCM6 acts as a tumor promoter by activating CDK4-Cyclin D1 signaling, and subsequently regulates cell cycle progression in G1/S phase in neuroblastoma." (PMID 34233647, 2021). "In neuroblastoma tumours, most showed increased expression of CCND1 compared to FA, where it was undetectable and there was a good correlation between GATA3 protein expression and CCND1 protein expression." (PMID 31831790, 2019). "Out of 8 cases of neuroblastoma in our series, 8(88.9%) demonstrated intense 3+ reactivity for Cyclin D1." (PMID 30736802, 2019). "All 8 cases of neuroblastoma in our study demonstrated intense 3+ staining for Cyclin D1 which ranged in extent from as low as 5% to as high as 90%." (PMID 30736802, 2019). "Most or all cases of CCSK, neuroblastoma and renal Ewing sarcoma demonstrated diffuse and strong positivity for Cyclin D1." (PMID 30736802, 2019). "Knock-down of GATA3 in neuroblastoma cell lines reduced CCND1 protein and RNA expression substantially." (PMID 31831790, 2019). "To further investigate the possible pathways by which GATA3 influences neuroblastoma proliferation, we examined cyclin D1 (CCND1), one of the known targets of GATA3 that is involved in cell cycle regulation." (PMID 31831790, 2019). "The mRNA and protein levels of MCL-1 and Cyclin D1 were reduced upon miR-193b overexpression in all neuroblastoma cell lines tested." (PMID 29719597, 2018). "Zingerone induced cell-cycle arrest at mitosis concurrently with inhibition of cyclin D1 expression in neuroblastoma cells." (PMID 30235818, 2018). "The current study shows that zingerone downregulates the expression of cyclin D1 in neuroblastoma cells, implying its action as a potential anti-cancer drug." (PMID 30235818, 2018). "The present study demonstrates that introduction of miR-193b into neuroblastoma cell lines results in a G1 cell cycle arrest via downregulation of cyclin D1." (PMID 29719597, 2018).
neuroblastoma (continued). "In the field of SRBCT and the overlap of nephroblastoma and neuroblastoma two recent reports propose immunohistochemical markers, cyclin D1 and PHOX2B, to be reliable for distinction of neuroblastoma from other malignancies." (PMID 28818093, 2017). "In this regard, focal amplifications of ALK, CCND1, LIN28B, MDM2, and 19q13.42 observed in our study have been previously implicated in individual neuroblastoma studies 8–12." (PMID 28924153, 2017). "Genetic aberrations of cyclin D1 (CCND1), including overexpression, have been reported in neuroblastoma." (PMID 25625291, 2015). "Cyclin D1 has also been studied to some extent in neuroblastoma and has previously been shown to be highly expressed in a subset of neuroblastoma cell lines and tumors due to gene amplification or GATA3 binding." (PMID 26225123, 2015). "We first measured the mRNA expression levels of CCND1 in a panel of 31 neuroblastoma cell lines and evaluated the effects of CCND1 knockdown on the proliferation of eight neuroblastoma cell lines in real time using the xCELLigence system." (PMID 26225123, 2015). "Collectively, the data suggest that YB-1 binds to the promoter of CCND1 and promotes its transcription in neuroblastoma cells in order to modulate cell proliferation." (PMID 25993060, 2015). "As inhibition of PLK1 using small molecule compounds has already been extensively studied in neuroblastoma, we decided to select CCND1 for further experiments." (PMID 26225123, 2015). "The effect of palbociclib on the proliferation of neuroblastoma cells is very similar to the effect induced by the knockdown of CCND1, which suggests that both treatments induce their effects by targeting the same pathway." (PMID 26225123, 2015). "Several cell cycle regulators, such as PLK1, TRIM16, WEE1, CDK4/6, and CCND1, have been shown to be involved in the tumorigenesis of neuroblastoma." (PMID 26225123, 2015). "Inhibition of the G1 regulating genes CDK4 or Cyclin D1 in neuroblastoma cell lines lead to the restoration of the G1 checkpoint and subsequent neuronal differentiation." (PMID 23383150, 2013). "Further, by co-expression experiments in transiently transfected mouse neuroblastoma Neuro 2a cells, we found that the Cend1-dependent or Dyrk1B-dependent down-regulation of cyclin D1 is reversed following their interaction with RanBPM." (PMID 24312406, 2013). "Specifically, we have demonstrated that Dyrk1B overexpression in mouse neuroblastoma cells promotes cell cycle exit and neuronal differentiation by phosphorylating cyclin D1, followed by its cytoplasmic relocation and subsequent degradation by the 26S proteasome." (PMID 38294527, 2024). "This suggested that one of major mechanisms by which GATA3 affects neuroblastoma cell proliferation may be via modulating CCND1 levels." (PMID 31831790, 2019). "We predicted that CCND1 expression might be maintained at a high rate in all stages, including stage 1 in neuroblastoma." (PMID 30235818, 2018). "Furthermore, dysregulated Hh signaling upregulates levels of Cyclin D1 which directly leads to excessive proliferation as Cyclin D1 facilitates the ability of cells to bypass the mitotic cellular checkmarks leading to MB formation and neuroblastoma." (PMID 26988232, 2016). "In the present study, the ability of EV71 to induce apoptosis was analyzed in the SH-SY5Y human neuroblastoma cell line and the effect of this virus on the mRNA expression levels of various apoptotic markers, miRNA let-7b and cyclin D1 (CCND1), was also investigated." (PMID 25779425, 2015).